ZBTB42 (zinc finger and BTB domain containing 42)
Description:
Transcriptional repressor. Specifically binds DNA and probably acts by recruiting chromatin remodeling multiprotein complexes.
Synonyms: ZNF925; LCCS6
Tractability: Antibody: its Gene Ontology location is reachable by antibodies, with high confidence.
Gene: Protein-coding gene on chromosome 14 (104,799,415 to 104,804,712, forward strand). Ensembl gene ENSG00000179627.
Subcellular location: Cytoplasm; Nucleus; Nucleus, nucleoplasm
Subcellular location (Human Protein Atlas): Nucleoplasm
Gene Ontology:
Molecular function: protein binding; DNA-binding transcription factor activity, RNA polymerase II-specific
Biological process: muscle organ development; regulation of transcription by RNA polymerase II
Cellular component: nucleoplasm; nucleus; cytoplasm
Genetic constraint (gnomAD): Loss-of-function variants: 6 observed, 6.99 expected, observed/expected ratio (o/e) 0.86, 90% interval 0.47 to 1.63. That is too few expected variants to judge how well the gene tolerates losing a copy. Missense variants: 505 observed, 525.56 expected, observed/expected ratio (o/e) 0.96, 90% interval 0.89 to 1.03. Synonymous variants: 243 observed, 235.45 expected, observed/expected ratio (o/e) 1.03, 90% interval 0.93 to 1.15.
Homologues: Orthologues: chimpanzee ZBTB42 (99% identical), macaque ZBTB42 (95% identical), pig ZBTB42 (79% identical), mouse Zbtb42 (76% identical), rat Zbtb42 (75% identical), zebrafish si:dkey-79d12.4 (23% identical). Paralogues in human: ZBTB18 (50% identical), HIC1 (23% identical), ZBTB1 (23% identical), ZBTB16 (21% identical), HIC2 (20% identical), ZBTB7C (18% identical), PATZ1 (16% identical), ZBTB20 (16% identical), PRDM1 (15% identical), ZBTB45 (15% identical), ZNF384 (15% identical), ZNF410 (15% identical), and 24 more.
Diseases named in the same sentence as ZBTB42 in open-access papers:
ZBTB42 is named in the same sentence as 10 diseases in open-access papers, as found by Europe PMC text mining. Sharing a sentence is not in itself a finding about the gene and the disease. The quoted sentences say what the papers report.
glioma (1 paper, 2023). A benign or malignant brain and spinal cord tumor that arises from glial cells (astrocytes, oligodendrocytes, ependymal cells). "What’s more, ZBTB42 is correlated with stem cell markers and positively associated with glioma stemness." (PMID 36762114, 2023). "In GSVA hallmark analysis, a similar result was detected, which confirmed the relativity between ZBTB42 and the glioma microenvironment." (PMID 36762114, 2023). "To elucidate the effect of ZBTB42 alteration on biological functions in glioma, we compared the high ZBTB42 expression group and low expression group in glioma and filtered out upregulated and downregulated genes." (PMID 36762114, 2023). "We divided the 631 TCGA glioma patients into high ZBTB42 expression and low expression groups by optimal cutoff point." (PMID 36762114, 2023). "Our data show increased ZBTB42 promotor and gene body methylation preference in benign subtypes of glioma, which is negatively related to ZBTB42 expression." (PMID 36762114, 2023). "To further understand the distribution of ZBTB42 in glioma with different clinical parameters, we analyzed the glioma patients from the CGGA-325 cohort, CGGA-693 cohort, and the TCGA dataset by the Brainbase website." (PMID 36762114, 2023). "Collectively, ZBTB42 is a prognostic biomarker of glioma and the hypomethylation of ZBTB42 is, at least partly, the reason for the promotion of ZBTB42 expression." (PMID 36762114, 2023). "The immunohistochemistry staining showed an evident ZBTB42 signal in different WHO grades of glioma samples." (PMID 36762114, 2023). "Here we first illustrated the ZBTB42 expression profile in pan-cancer and investigated its potential relationship with glioma." (PMID 36762114, 2023). "To further illustrate the potential role of ZBTB42 in glioma, we applied Lasso regression on the DEGs between the high ZBTB42 expression group and low expression group in LGG patients." (PMID 36762114, 2023). "In this study, we found abnormally high expression of ZBTB42 in glioma and verified this discovery with clinical glioma samples and cultured cells." (PMID 36762114, 2023). "The quantification analysis of area optical density (AOD) indicated that ZBTB42 is higher expressed in glioma tissues compared with normal brain tissue." (PMID 36762114, 2023). "ZBTB42 is positively related to glioma stem cells marker genes such as CD44, MSI1, Fut4, and NES and the high expression group has a stronger relationship with glioma stemness." (PMID 36762114, 2023). "Taken all together, we speculated that dysregulation of ZBTB42 in glioma affects glioma progression via the tumor microenvironment, especially the immune microenvironment." (PMID 36762114, 2023). "In GSE4290, GSE50161, and GSE59612, ZBTB42 expression is highly elevated in glioma and GBM." (PMID 36762114, 2023). "ZBTB42 is related to immune suppression and glioma stemness in the microenvironment." (PMID 36762114, 2023). "ZBTB42 expression knockdown with shRNA in glioma cells induced decreased growth ability." (PMID 36762114, 2023). "On the other hand, glioma patients with high expression of ZBTB42 usually comprise higher stemness of glioma which may be another aspect of ZBTB42 potential function in glioma." (PMID 36762114, 2023). "Then we asked does ZBTB42 deregulation plays a role in the progression of glioma." (PMID 36762114, 2023). "Interestingly, the level of ZBTB42 expression increased with the improvement of the WHO grade in all glioma datasets." (PMID 36762114, 2023). "In the correlation analysis, ZBTB42 is positively related to the expression of CSF-1 in both LGG and GBM indicating ZBTB42 is associated with immune suppression in glioma and this feature may be related to the increased expression of CSF-1." (PMID 36762114, 2023). "In summary, we have identified ZBTB42 as a novel prognostic biomarker for glioma." (PMID 36762114, 2023).
glioma (continued). "Meanwhile, we found that in the GTEx dataset, ZBTB42 is lowly expressed in brain tissue which indicated that ZBTB42 may play a role in the development of glioma." (PMID 36762114, 2023). "Therefore, we asked if ZBTB42 is related to the stemness of glioma." (PMID 36762114, 2023). "Targeting ZBTB42 treatment may help glioma patients have better overall survival." (PMID 36762114, 2023). "Furthermore, we performed ZBTB42 RT-qPCR on glioma and normal brain tissue." (PMID 36762114, 2023). "In both LGG and GBM, ZBTB42 was positively related to CSF1, which is known for promoting glioma immune suppression." (PMID 36762114, 2023). "Interestingly, the expression of ZBTB42 was increased in stem-like, differentiation-like, and proliferation stem-like cells after radiation, indicating that ZBTB42 wasn’t only related to the stemness of glioma but also may play a role in radiation resistance in glioma treatment." (PMID 36762114, 2023). "Here, we find that ZBTB42, a member of the ZBTB transcription factor family, is a new biomarker for glioma." (PMID 36762114, 2023). "ZBTB42 is amplified in .6% of glioma patients and most of which are IDH wild-type glioma." (PMID 36762114, 2023). "More interestingly, ZBTB42 is almost never expressed in the normal brain while highly expressed in glioma tissue, but its mechanism of regulating glioma progression is still unknown." (PMID 36762114, 2023). "However, the function of ZBTB42 in glioma development has not been studied by now." (PMID 36762114, 2023). "Correlation analysis showed that ZBTB42 was positively related to PD1, PD-L1, PD-L2, CTLA4, TIM3, and LAG3 in LGG and positively related to PD-L1, PD-L2, SIRPA in GBM, suggesting that the high expression of ZBTB42 may promote glioma progression via immune suppression microenvironment." (PMID 36762114, 2023).
lethal congenital contracture syndrome (1 paper, 2023). A syndrome characterized by congenital nonprogressive joint contractures. "ZBTB42 is known to be expressed in skeletal muscle and testis and mutation of ZBTB42 leads to Lethal congenital contracture syndrome (LCCS)." (PMID 36762114, 2023).
tumor (1 paper, 2023). "In ssGSEA analysis, tumor proliferation-related signatures and extracellular matrix signatures such as angiogenesis, protumor cytokines, tumor proliferation rate, and matrix remodeling were also significantly improved in the high ZBTB42 expression group." (PMID 36762114, 2023). "In GBM, the Stromal score, Immune score, and ESTIMATE score were higher and the tumor purity was lower in the high ZBTB42 expression group." (PMID 36762114, 2023). "Therefore, the demethylation of the promoter and body may result in the increased expression of ZBTB42, and abnormal expression of ZBTB42 reveals a more severe tumor progression." (PMID 36762114, 2023).
ZBTB42 also shares sentences with these, for which no sentence is quoted: cancer (2 papers); breast carcinoma (1); glioblastoma (1); ovarian serous cystadenocarcinoma (1); prostate adenocarcinoma (1); thymoma (1); uterine corpus endometrial carcinoma (1).